NF1 (neurofibromin 1)
Diseases named in the same sentence as NF1 in open-access papers (continued):
Sharing a sentence is not in itself a finding about the gene and the disease.
breast cancer (continued). "Although Ras/MAPK activating mutations are rare in breast cancer, they can occur infrequently, and we and others have previously reported loss of Ras/MAPK negative regulators (DUSP4, NF1, RND1) in breast cancer as a mechanism of pathway activation." (PMID 32634121, 2020). "In other studies, inhibitors of PI3K, the downstream effector of the Ras pathway, were shown to inhibit the growth of NF1-mutated MPNST cells and neurofibromin-deficient human breast cancer xenografts in mice." (PMID 33061844, 2020). "A link between NF1 and breast cancer has been suggested in several cohort and epidemiological studies and numerous cases of patients with NF1 presenting with breast cancer have been reported." (PMID 30962859, 2019). "Nf1-deficient rat models were recently developed to evaluate the effect of Nf1 on tumorigenesis; Nf1 mammary tumors are positive for estrogen receptor and highly express pan-cytokeratins." (PMID 31466283, 2019). "When separated by age, the median survival of the female NF1 patients with breast cancer identified in this study was 5.58 years in those < 50 years of age and over 15 years in those ≥50 years of age." (PMID 30962859, 2019). "The median age at time of breast cancer death was found to be 48.5 years in this group of NF1 breast cancer cases compared to 68 years in the general population reported in the SEER database." (PMID 30962859, 2019). "Based on a random-effects model, the combined SIR of breast cancer for all women with NF1 was 3.07 (95% CI: 2.16–4.38)." (PMID 30962859, 2019). "Since then, 41 additional case reports/case series have been reported describing an additional 74 females with NF1 that developed breast cancer." (PMID 30962859, 2019). "The female NF1 patients with breast cancer originated from 23 different countries, with the majority of them originating from the United States of America (38%), United Kingdom (31%), and Japan (12%)." (PMID 30962859, 2019). "The median survival for all of the identified cases of NF1 women with breast cancer was 5 years compared to the reported median breast cancer survival of over 20 years in the general population using the SEER data base." (PMID 30962859, 2019). "Descriptive analysis of these 286 reported cases of NF1 and female breast cancer demonstrated a median age of 46 years at time of breast cancer diagnosis, compared to 62 years in the general population reported in the SEER database." (PMID 30962859, 2019). "The relative survival of the female NF1 patients with breast cancer identified in this study was compared to the general population using the SEER database controlling for age and year at diagnosis for each patient." (PMID 30962859, 2019). "Obviously, we can see that NF1, BRCA1, FOXO1, PTEN, CAV1 and WT1 are linked with breast cancer genes in PPI network or pathway network." (PMID 31760937, 2019). "Given that this study demonstrated a peak age of breast cancer diagnosis between 35 and 44 years of age in these patients with NF1, this study provides further evidence for early breast cancer screening starting at 30 years of age in women with NF1." (PMID 30962859, 2019). "When analyzing all the female NF1 patients with breast cancer, the majority presented with stage I or II disease." (PMID 30962859, 2019).
breast cancer (continued). "Patient 2 – a 63-year-old lady with a history of NF-1-related phaeochromocytoma 20 years ago and previous breast cancer presented with a new adrenal lesion on the contralateral side." (PMID 30909165, 2019). "Continued education of the general public and primary health care providers will allow for appropriate implementation of the most recent NCCN breast cancer screening guidelines in all young women with NF1 starting at 30 years of age." (PMID 30962859, 2019). "To address this gap in the literature, we sought to evaluate the level of uptake with recommended breast cancer screening among women with NF1 enrolled in a government-funded cancer screening program." (PMID 31121919, 2019). "This is in line with previous studies demonstrating a higher prevalence of grade II and III breast cancers diagnosed among women with NF1 between the ages of 40–60." (PMID 31121919, 2019). "Patient 1, carrying NF1:c.122A>T, which introduces a new exonic 5’ donor splice site, was diagnosed with hormone-positive, Her-2-negative breast cancer at the age of 47." (PMID 31507634, 2019). "To evaluate NF1 in human breast cancer, we analyzed genomic changes in a data set of 2000 clinically annotated breast cancers." (PMID 30182054, 2018). "To evaluate the impact of NF1 in sporadic breast cancer we analyzed genomic changes in a large breast cancer data set composed of >2000 clinically annotated breast cancers." (PMID 30182054, 2018). "Here we present data that illuminates the role that NF1 plays in breast cancer and a novel model for interrogating the interaction between NF1 and ER in both sporadic and NF-related breast cancer." (PMID 30182054, 2018). "We found NF1 shallow deletions in 25% of sporadic breast cancers, which correlated with poor clinical outcome." (PMID 30182054, 2018). "Immunostaining of several tumors revealed that the Nf1 mammary tumors were positive for estrogen receptor, progesterone receptor, and HER2/Neu receptor and highly proliferative based on Ki67 staining." (PMID 30182054, 2018). "Mammary tumors with acinar, solid, ductular, and cystic histology were observed in tumors in Nf1 female rats from each line." (PMID 30182054, 2018). "Histopathologic analysis of the mammary tumors revealed that both Nf1 in-frame deletions and premature stop indels induced a wide variety of histopathologic mammary tumor types." (PMID 30182054, 2018). "This aggressive mammary phenotype was highly penetrant and multifocal mammary tumors were observed in the subsequent G1 and G2 generations from each of the Nf1 lines, including lines derived from male founders." (PMID 30182054, 2018). "It was Ogata and colleagues, working with established breast cancer cell lines in 2001, who first identified a role for NF1 in the malignant transformation of mammary cells." (PMID 28637487, 2017). "In conclusion, these results suggest that miR-10b stimulates the expression of c-Jun in metastatic breast cancer cells through RhoC and NF1." (PMID 27494896, 2016). "(ii) Overexpression of NF1 in metastatic breast cancer cells decreased c-Jun levels, while NF1 knockout in mouse embryonic fibroblasts elevated the accumulation of c-Jun considerably." (PMID 27494896, 2016). "They concluded that the concurrence of NF1 and breast cancer was probably due to the simultaneous existence of two cancer-predisposing conditions." (PMID 25885768, 2015). "The data showing a high prevalence and a possible earlier onset of breast cancer in NF1 individuals have important implications on screening." (PMID 25885768, 2015). "The patients and physicians should be aware of the high possibility of breast cancer in individuals with NF1." (PMID 26604930, 2015). "With regard to this, various authors have suggested different mechanisms supporting the relationship between NF1 and breast cancer." (PMID 25885768, 2015).
breast cancer (continued). "Because breast cancer is a common tumor in the general female population, the exact relationship between NF1 and breast cancer has been debated." (PMID 25885768, 2015). "Further studies are needed to clarify the relationship between NF1 and breast cancer, especially at the genetic level, and to establish specific screening guidelines for the early diagnosis of breast cancer in NF1 patients." (PMID 26604930, 2015). "Several other clinical cases of NF1 patients with breast cancer were subsequently presented in the literature." (PMID 25885768, 2015). "The authors reached the conclusion that women with NF1 had five times more chances of developing breast cancer when compared to the general population." (PMID 25889501, 2015). "We report the cases of three white Arabic women presenting with breast cancer and a previous diagnosis of NF1, and review the available data in the literature." (PMID 25889501, 2015). "We report a case of a 54-year-old woman with NF1 and the challenge involved in detecting an advanced breast cancer because of numerous skin neurofibromas." (PMID 25885768, 2015). "The most common histopathological type of breast cancer in NF1, as well as in the general population, is infiltrating ductal carcinoma, as observed in our case." (PMID 25885768, 2015). "C57Bl/6/129Sv Nf1+/- mice exposed to focal, fractionated ionizing radiation developed diverse malignancies, including soft tissue sarcomas, mammary carcinomas and squamous cell carcinomas." (PMID 26000738, 2015). "In the present case, a 53-year-old woman with NF1 presented with a very aggressive breast cancer which metastasized to mandible, ribs, lung, and liver." (PMID 24876981, 2014). "Breast cancer in NF1 patients appears to have an aggressive phenotype in the two reported case series." (PMID 25026295, 2014). "In contrast, NF1 isoforms were determined to shift from the type II mRNA isoform in normal breast in normal breast cancer to the type I mRNA isoform in breast carcinoma." (PMID 25051360, 2014). "27.7% of human breast cancers in the TCGA project were subsequently found to harbour NF1 aberrations, majority of which were heterozygous deletions." (PMID 25026295, 2014). "Knockdown of NF1 with siRNA induced the expression of these transcription factors in normal human Schwann cells as well as epithelial-like breast cancer cell lines." (PMID 25026295, 2014). "NF1 and Ras expression were examined in 22 sporadic breast cancers, 18 benign lesions and 6 normal breast tissues by tissue microarrays." (PMID 25051360, 2014). "Similar to our case, McMillan and Edwards reported a case of bilateral mandibular metastases of breast carcinoma in a 41-year-old woman with NF1." (PMID 24876981, 2014). "Intriguingly, transcriptional activation of the mouse mammary tumour retrovirus is dependent on H3S10ph and hyperacetylation of H3, mediated by binding of the nuclear factor 1 (NF-1) transcription factor to the proviral LTR." (PMID 21774827, 2011). "Owing to the paucity of reports of NF1 and breast cancer, Riccardi commented that an association between these two types of diseases cannot be firmly established, but recommended molecular analysis of breast cancers in NF1 patients." (PMID 20205809, 2010). "The data suggesting a possible earlier onset of breast cancer in individuals with NF1 are particularly important, given the possible screening implications." (PMID 16786042, 2006). "Here, we present a personalized treatment model using a patient-derived Networking Organoid Culture System (NOCS) composed of intestinal, liver, and kidney organoids differentiated from induced pluripotent stem cells (iPSCs) of an NF1-mutant breast cancer patient." (PMID 41781386, 2026).
breast cancer (continued). "Notably, NF1 and PICK3CA mutations frequently co-occur in a metastatic breast cancer cohort (odds ratio = 1.75, p < 0.001), suggesting convergent signaling pathways that drive metastatic progression." (PMID 41226361, 2025). "To determine whether NF1 inactivation acts alone or cooperates with other oncogenic events in early-stage breast cancer to promote progression to aggressive disease, we analyzed METABRIC data using Fisher’s exact test." (PMID 41226361, 2025). "While women with NF1 over 50 years of age do not differ significantly in breast cancer risk compared to women in the general population, those younger than 50 years have an up to five-fold increased risk." (PMID 38859614, 2025). "Many pathogenic gene mutations common to breast cancer, such as Pten, Brca2, Atm, Cdh1, Chek2, Nf1, Arid1a, Pik3ca, and Esr1, revealed no alterations between NT2.5 and NT2.5-LM." (PMID 38717519, 2024). "Additionally, our analysis of the METABRIC breast cancer dataset showed that patients with NF1 shallow deletions are 1.65 times more likely to die within the first 10 years compared to patients with diploid NF1 status." (PMID 38799507, 2024). "Her medical history was NF1, and her surgical history was bilateral mastectomy for breast cancer." (PMID 38282102, 2024). "With the goal of uncovering non-epithelial contributions to NF1-related breast cancer tumorigenesis, we measured alterations in the Nf1-deficient mammary stromal region before tumor formation." (PMID 38799507, 2024). "In addition, the proportional mortality rate of breast cancer patients with NF1 was 3.5 (95% confidence interval 1.3–7.7)." (PMID 38282102, 2024). "Despite the known impact of collagen in breast cancer as well as other NF1-related tumors, the contribution of collagen in NF1-associated breast cancer has not been characterized." (PMID 38799507, 2024). "Notably, within our findings, we identified a higher incidence of breast cancer in patients with NF1, which presented with an early onset." (PMID 38686623, 2024). "In addition, another study suggested that 5-year overall survival of patients with breast cancer and NF1, after age and estrogen receptor expression level matched, was poorer than breast cancer patients without NF1." (PMID 38282102, 2024). "NF1-related breast cancers are associated with adverse prognostic factors, aggressive molecular subtypes (HER2+ and triple-negative breast cancers), and decreased overall survival compared to sporadic breast cancer." (PMID 38799507, 2024). "NF1 associated breast cancer was more often oestrogen receptor negative, progesterone receptor negative and human epidermal growth factor receptor 2 (HER2) positive, which are all factors correlated with a poor prognosis." (PMID 36684394, 2023). "Additionally, screening for breast cancer in patients with NF1, preferably with annual breast MRI, should begin at 30 years." (PMID 36684394, 2023). "Therefore, in this study, we took a proteogenomic approach to optimize the determination of NF1 protein levels directly in breast cancer samples." (PMID 37501682, 2023).
breast cancer (continued). "Indeed, our findings demonstrate that women with NF1 are less likely than the general population to undertake breast cancer screening at the recommended age, with younger women less knowledgeable about when to start surveillance." (PMID 36444392, 2023). "The AURORA study found KRAS and NF1 to be among the significantly mutated driver genes in breast cancer but not enriched in metastatic lesions." (PMID 36358725, 2022). "A subset of another 10 subjects had additional NF1‐related tumors, including neoplasms in female genital organs (n = 4), multiform glioblastoma (n = 1), breast cancer (n = 1), gastrointestinal stromal tumor (n = 1), pheochromocytoma (n = 1), ganglioneuroma, and prolactinoma (n = 1)." (PMID 35506373, 2022). "The link between NF1 and breast cancer has recently been established, with patients with NF1 being at higher risk for developing breast cancer, more likely to get breast cancer at a younger age, and more likely to have their breast cancer present with more adverse prognostic factors." (PMID 33842116, 2021). "A breast cancer 2 (BRCA2) positive woman with NF1 and chronic lymphocytic leukemia is described." (PMID 33954070, 2021). "The NF1 gene has been identified as a tumour suppressor gene due to its involvement in the Ras pathway, with NF1 dysfunction leading to Ras overexpression - significant as Ras overexpression is responsible for as many as 60% of breast cancer cases." (PMID 33842116, 2021). "A previous work suggested that NF1 deletions would not be responsible for an increased risk for breast cancer as no cases were observed in patients with NF1 deletions in this report." (PMID 34199217, 2021). "Since most symptomatic patients are tested for NF1 mutations before they visit a breast cancer clinic, these patients are not tested for mutations in BRCA1/2 genes for their breast disease, a requisite for enrollment in the current study." (PMID 32566746, 2020). "Both of these approaches identified driver gene mutations in breast cancer-associated genes, such as MUC16, NF1, and BRCA2, suggesting that using different predictive computational tools improves the sensitivity and specificity in identifying cancer somatic mutations." (PMID 32650480, 2020). "Accordingly, NF1 loss correlates with tamoxifen resistance in ER+ breast cancers, and co-targeting of MEK and ER may improve treatment of NF1-deficient tumors." (PMID 33096593, 2020). "This increased risk of breast cancer was not seen for NF1 patients 50 years of age or older; SIR = 0.59 (95% CI: 0.02–3.33)." (PMID 30962859, 2019). "The peak age of breast cancer diagnosis in these NF1 women was between 34 to 44 years." (PMID 30962859, 2019). "Interestingly, three of the four women diagnosed with breast cancer in our NF1 cohort had a positive family history of breast cancer." (PMID 31121919, 2019).